ABCA5 (ATP binding cassette subfamily A member 5)
Description:
Cholesterol efflux transporter in macrophages that is responsible for APOAI/high-density lipoproteins (HDL) formation at the plasma membrane under high cholesterol levels and participates in reverse cholesterol transport. May play a role in the processing of autolysosomes (By similarity).
Synonyms: EST90625; ABC13; DEL17q24; HTC3; HTGH
Tractability: Antibody: UniProt places it where antibodies can reach, with medium confidence; UniProt predicts a signal peptide or a membrane-spanning region; its Gene Ontology location is reachable by antibodies, with medium confidence. PROTAC: ubiquitination databases record sites on it; its protein half-life has been measured.
Gene: Protein-coding gene on chromosome 17 (69,244,311 to 69,327,244, reverse strand). Ensembl gene ENSG00000154265.
Subcellular location: Golgi apparatus membrane; Lysosome membrane; Late endosome membrane; Cell membrane
Subcellular location (Human Protein Atlas): Nucleoplasm
Pathways (Reactome):
Transport of small molecules: ABC transporters in lipid homeostasis
Gene Ontology:
Molecular function: ATPase-coupled transmembrane transporter activity; lipid transporter activity; ABC-type transporter activity; ATP binding; ATP hydrolysis activity
Biological process: cholesterol homeostasis; cholesterol metabolic process; regulation of cholesterol efflux; cholesterol efflux; high-density lipoprotein particle remodeling; lipid transport; negative regulation of macrophage derived foam cell differentiation; positive regulation of reverse cholesterol transport; reverse cholesterol transport; transmembrane transport
Cellular component: Golgi membrane; late endosome; late endosome membrane; lysosomal membrane; lysosome; plasma membrane; membrane
Genetic constraint (gnomAD): Loss-of-function variants: 88 observed, 108.3 expected, observed/expected ratio (o/e) 0.81, 90% interval 0.68 to 0.97. The upper end of that interval is the gene's LOEUF score, 0.97, which puts it in group 4 of 6, group 1 being the genes least tolerant of losing a copy. Missense variants: 1,282 observed, 1,315.5 expected, observed/expected ratio (o/e) 0.97, 90% interval 0.93 to 1.02. Synonymous variants: 420 observed, 428.61 expected, observed/expected ratio (o/e) 0.98, 90% interval 0.9 to 1.06.
Homologues: Orthologues: chimpanzee ABCA5 (99% identical), macaque ABCA5 (98% identical), dog ABCA5 (93% identical), rabbit ABCA5 (93% identical), pig ABCA5 (91% identical), rat Abca5 (90% identical), mouse Abca5 (90% identical), guinea pig ABCA5 (86% identical), tropical clawed frog abca5 (57% identical), Caenorhabditis elegans abt-2 (21% identical), Drosophila melanogaster CG31213 (20% identical), Drosophila melanogaster ldd (20% identical), and 5 more. Paralogues in human: ABCA8 (41% identical), ABCA9 (41% identical), ABCA10 (40% identical), ABCA6 (40% identical), ABCA1 (27% identical), ABCA2 (26% identical), ABCA4 (26% identical), ABCA7 (25% identical), ABCA12 (25% identical), ABCA13 (25% identical), ABCA3 (25% identical).
Diseases named in the same sentence as ABCA5 in open-access papers:
ABCA5 is named in the same sentence as 52 diseases in open-access papers, as found by Europe PMC text mining. Sharing a sentence is not in itself a finding about the gene and the disease. The quoted sentences say what the papers report.
hypertrichosis (5 papers, 2014 to 2024). Excessive hair growth anywhere on the body. "Although the hypertrichosis has been attributed to deletion of the ABCA5 gene, the cause of the gingival hyperplasia observed in some of these patients is less clear." (PMID 39257002, 2024). "ABCA5 is highly expressed in human skin and hair follicles and bi-allelic loss-of-function mutations in ABCA5 are linked to excessive hair overgrowth (hypertrichosis)." (PMID 35477481, 2022). "ABCA5, a putative cholesterol transporter implicated in a form of heritable hypertrichosis also localised to both the plasma membrane and intracellular compartments." (PMID 33404706, 2021).
osteosarcoma (5 papers, 2012 to 2023). A usually aggressive malignant bone-forming mesenchymal neoplasm, predominantly affecting adolescents and young adults. "In humans, ABCA5 is a reported biomarker for tumor stem cells in osteosarcoma based on its overexpression, where it is also highly expressed in melanoma and undifferentiated colon and ovarian carcinomas." (PMID 24831815, 2014). "ABCA5 expression was comparable between osteosarcoma and primary osteoblasts, but osteosarcoma metastasized to lung showed significantly higher ABCA5 expression when compared with primary osteoblasts." (PMID 22870217, 2012). "For both CBX3 and ABCA5, comparable expression was observed between osteosarcoma and osteosarcoma metastasized to lung." (PMID 22870217, 2012). "In addition, proteomic and transcriptome analyses revealed high expression of chromobox protein homolog 3 (CBX3) and ABCA5, respectively, which was significantly higher in osteosarcoma than in primary osteoblast." (PMID 28115942, 2016). "ABCA5 was identified as a putative biomarker of TSCs and/or osteosarcoma." (PMID 22870217, 2012). "Possibly due to their mesenchymal origin, osteosarcoma CSCs are proved to preferentially express MSC markers, such as CD133, CD117/Stro-1, CBX3/ABCA5." (PMID 24893164, 2014). "Since stem-like cells in bone sarcoma were firstly detected by Gibbs, multiple markers have been employed to identify CSCs of osteosarcoma, such as CD133, CD117/Stro-1, CBX3/ABCA5." (PMID 24893164, 2014). "Identification of ABCA5 and CBX3 in TSC-enriched spheres fulfilled our goal of finding osteosarcoma biomarker candidates that could be used in combination with already known markers, such as ABCG2 and ALDH." (PMID 22870217, 2012). "Significantly higher ABCA5 expression, a relatively newly discovered ABC transporter, in CHA59 and Saos-2 spheres vs. monolayers points to its utility as a putative TSC-enrichment marker in osteosarcoma." (PMID 22870217, 2012).
lysosomal storage disorder (4 papers, 2014 to 2024). "A clue to the possible function of ABCA5 in PD comes from a 2005 study, which showed that deletion of Abca5 in mice replicated a lysosomal storage disorder similar to Gaucher’s disease." (PMID 38212656, 2024).
Alzheimer disease (3 papers, 2022 to 2025). A progressive, neurodegenerative disease characterized by loss of function and death of nerve cells in several areas of the brain leading to loss of cognitive function such as memory and language. "Differentially expressed ATP metabolism genes, such as that of the mitochondrially-encoded ATP synthase membrane subunit 6 (mt-ATP6), Atp2b2 and Abca5, are associated with neuropathologies/neurodegenerations, like Alzheimer’s disease and autism." (PMID 39715923, 2025). "Diseases associated with ABCA5 cholesterol transport function include Alzheimer's disease, Parkinson's disease, ST-segment elevation myocardial infarction, atherosclerosis, and excessive hair growth." (PMID 35783152, 2022).
breast carcinoma (3 papers, 2012 to 2023). "Although a significant body of literature has linked ABCG2 expression with drug resistance in breast cancer, considerably less is known about ABCA5 and ABCC5 in this disease." (PMID 23174366, 2012). "This is consistent with the expression pattern of ABCA5 in breast cancer, suggesting that ABCA5 plays an oncogene role in colorectal and breast cancers." (PMID 35783152, 2022). "Conversely, genes on chromosome 17 region “Nikolsky Breast Cancer 17q21-q25” were amplified in CR and contained ATP-binding cassette (ABC) transporters (ABCA5/ABCA6/ABCA8/ABCA9/ABCA10) among them (172 genes total, FDR = 7.39E−178)." (PMID 37012431, 2023). "Intriguingly, three members of the ATP-binding cassette (ABC) transporter family (ABCA5, ABCC5, ABCG2) were overexpressed in breast cancer bone metastases compared with primary tumors that are metastatic to bone." (PMID 23174366, 2012). "Intriguingly, several members of the ATP-binding cassette (ABC) transporter superfamily (ABCA5, ABCC5, and ABCG2) were consistently overexpressed in breast cancer bone metastases compared with primary breast tumors." (PMID 23174366, 2012).
colon cancer (3 papers, 2022 to 2023). "Therefore, ABCA5 induction could be associated with the differentiation state of human colon cancer and contribute to the growth of tumours." (PMID 36674859, 2023). "A positive association was found between the expression level of ABCA5 and the infiltration levels of B cells, CD8+ T cells, CD4+ T cells, macrophages, neutrophils, and dendritic cells in colon cancer tissues (P < 0.05)." (PMID 35783152, 2022).
gingival hyperplasia (3 papers, 2014 to 2025). "Interestingly, ABCA5 lies in the minimal common region to four reported familial cases and one sporadic case of autosomal dominant CGHT, both with and without gingival hyperplasia, suggesting that mutations in this gene may be associated with CGHT." (PMID 24831815, 2014).
ovarian carcinoma (3 papers, 2014 to 2021). A malignant neoplasm originating from the surface ovarian epithelium. "ITGAV and ABCA5 have been reported to be associated with ovarian cancer and ADIPOQ and PPARG are associated with polycystic ovary syndrome." (PMID 35052428, 2021). "Low expression of ABCA5 was reported to be indicative of a poor outcome in ovarian cancer, with increased expression associated with an improved overall survival." (PMID 26040699, 2015).
Parkinson disease (3 papers, 2022 to 2024). A progressive degenerative disorder of the central nervous system characterized by loss of dopamine producing neurons in the substantia nigra and the presence of Lewy bodies in the substantia nigra and locus coeruleus. "Moreover, ABCA5 was implicated in the neuropathology associated with Alzheimer’s and Parkinson’s disease." (PMID 36980356, 2023). "Similar changes were observed with α-synuclein in neurons of the amygdala, where Parkinson’s disease patients showed higher levels of ABCA5." (PMID 36980356, 2023).
atherosclerosis (2 papers, 2022 to 2024). A disease characterized by the build-up of fatty material and calcium deposition in the arterial wall resulting in partial or complete occlusion of the arterial lumen. "Another study identified ABCA5 as a mediator of cholesterol efflux in macrophages under high-cholesterol conditions, highlighting its potential in lipid management and atherosclerosis." (PMID 39640258, 2024).
Lysosomal disease (2 papers, 2023 to 2024). "ABCA5 is located in the lysosomes and late endosomes and its homozygous knockout results in lysosomal disease like symptoms in mice." (PMID 37091798, 2023). "Knockout of murine ABCA5 leads to lysosomal-disease–like symptoms." (PMID 39640258, 2024).
prostate carcinoma (2 papers, 2012 to 2015). A carcinoma that arises from epithelial cells of the prostate gland. "The ABCA5 protein was detectable in basal cells of normal prostate glands and premalignant lesions, but was faintly expressed in prostate cancer glands." (PMID 26459268, 2015). "ABCA5 was reported as a marker in prostate cancer biopsies and urine." (PMID 22870217, 2012).
anemia (1 paper, 2016). A reduction in the number of red blood cells, the amount of hemoglobin, and/or the volume of packed red blood cells. "ABCA5 is a member of the ATP-binding cassette transporter 1 subfamily of genes whose mutations are linked to several human genetic disorders including cystic fibrosis, neurological disease, retinal degeneration, cholesterol and bile transport defects, anemia, and drug response phenotypes." (PMID 27755556, 2016).
colorectal cancer (1 paper, 2022). A primary or metastatic malignant neoplasm that affects the colon or rectum. "High expression was associated with a better prognosis, suggesting that ABCA5 overexpression was a protective response in colorectal cancer." (PMID 35783152, 2022). "It was the first time we demonstrated the diagnostic and prognostic value of ABCA5 in patients with colorectal cancer." (PMID 35783152, 2022). "In addition, in colorectal cancer patients, low expression level of ABCA5 was associated with shorter overall survival, similar to the expression pattern of ABCA5 in plasmacytic ovarian cancer." (PMID 35783152, 2022). "Our study showed that ABCA5 was down-expressed in colorectal cancer patient tissues compared to normal controls." (PMID 35783152, 2022). "The results of immune infiltration analysis showed the correlation between ABCA5 expression and immune infiltration of colorectal cancer." (PMID 35783152, 2022). "In colorectal cancer patients, patients with high expression of ABCA5 had a better prognosis than those with low expression of ABCA5." (PMID 35783152, 2022). "This indicates that ABCA5 may have an important effect in the development of colorectal cancer through cholesterol and macrophages." (PMID 35783152, 2022). "ABCA5 and ABCA8 were lowly expressed in cancer tissues, and ABCC1 was highly expressed in colorectal cancer tissues." (PMID 35783152, 2022).
epilepsy (1 paper, 2025). A brain disorder characterized by episodes of abnormally increased neuronal discharge resulting in transient episodes of sensory or motor neurological dysfunction, or psychic dysfunction. "There were 8 proteins shared between epilepsy and ischemic stroke: SH3BGRL3, BPNT1, PTPMT1, PACSIN3, MIPEP, CMC2, ABCA5, and PTK2B." (PMID 40624693, 2025).
esophageal cancer (1 paper, 2012). A primary or metastatic malignant neoplasm involving the esophagus. "A recent study reported a significantly higher ABCA5 expression in Hoechst 33342-labeled side-population vs. non-side population cells in esophageal cancer." (PMID 22870217, 2012).
Generalized hypertrichosis (1 paper, 2020). Generalized excessive, abnormal hairiness. "Congenital generalized hypertrichosis (OMIM 135400) is a rare disease with varying presentations and comorbidities that is speculated to be, at least in part, caused by loss of ABCA5 function." (PMID 32206879, 2020).
lung adenocarcinoma (1 paper, 2023). A carcinoma that arises from the lung and is characterized by the presence of malignant glandular epithelial cells. "Zhang and collaborators (2021) have identified seven N6-methyladenosine-related immune prognostic genes (i.e., PSMD10P1, DIDO1, ABCA5, CIITA, PRC1, ZWILCH, and ANLN) for lung adenocarcinoma (LUAD)." (PMID 37189849, 2023).
ovarian disease (1 paper, 2021). "In addition, four ovarian DEGs (ABCA5, ADIPOQ, ITGAV, and PPARG) in the FM_1-vs-NM_1 group are associated with negative regulation of macrophage-derived foam cell differentiation and are all involved in ovarian disease." (PMID 35052428, 2021).
prostatic tumor (1 paper, 2015). "In addition to ABCA11, the extra-prostatic tumor stage (pT3 vs pT2) was associated with the down-regulation of other ABC transporter genes from subfamily A: ABCA5 (FC 1.73; p = 0.022), ABCA6 (FC 2.00; p = 0.046), and ABCA10 (FC 3.29; p = 0.006)." (PMID 26459268, 2015).
rectal cancer (1 paper, 2022). A primary or metastatic malignant neoplasm that affects the rectum. "In rectal cancer, the expression level of ABCA5 was positively correlated with the infiltration level of B cells and CD8+ T cells, while it was not significantly different from the infiltration level of CD4+ T cells, macrophages, and neutrophils." (PMID 35783152, 2022). "The survival analysis of ABCA5, ABCA8, and ABCC1 genes was performed in the TCGA colon and rectal cancer (TCGA-COADREAD) and GSE24551-GPL5175 datasets." (PMID 35783152, 2022).
serous ovarian cancer (1 paper, 2021). "Low expression of ABCA5 is associated with poor prognosis of serous ovarian cancer." (PMID 34122496, 2021).
cancer (7 papers, 2010 to 2023). A tumor composed of atypical neoplastic, often pleomorphic cells that invade other tissues. "Perhaps it can be understood that the high expression of ABCA5 is to maintain the balance of cholesterol transport, which would reduce the cholesterol content in cancer cells." (PMID 35783152, 2022). "Similarly, ABCA5 showed increased expression in the laryngeal Hep-2 cancer cell lines that became resistant to a higher dose of 5-fluorouracil, indicating the possible role of ABCA5 in cancer chemoresistance." (PMID 36674859, 2023). "In addition, we have done a pan-cancer analysis of ABCA5 with immune cells." (PMID 35783152, 2022). "Among them, ABCA5 is a member of the ATP binding cassette (ABC) transporters, which play a variety of roles in cancer biology and drug resistance." (PMID 34122496, 2021). "Furthermore, after treatment with a compound that sensitized chemoresistant CRC cells to anti-cancer drugs, it was observed that the overexpressed ABC transporters such as ABCA5 were downregulated." (PMID 36674859, 2023). "For example, ABCA5, ADAMTS12 and CLEC3B have not been reported to be cancer related." (PMID 21060876, 2010).
tumor (6 papers, 2011 to 2025). "Two well known genes, ABCG2 and ABCA5 that involved in drug resistance in many types of tumor were overexpressed in CD44H cells." (PMID 21731740, 2011). "To find out the relationship between patient survival status and clinical characteristics, we performed a univariate Cox regression analysis, including age, gender, clinical stage, T stage, M stage, N stage, tumor tissue site, and transcript expression level of ABCA5 gene." (PMID 35783152, 2022).
genetic disease (2 papers, 2014 to 2016). "Moreover, a query for genetic variants that lie within the ABCA5 locus using the UCSC Human Genome (hg19) and Ensemble Genome Browsers verified that this variant is not a SNP or common variant associated with any human genetic disease." (PMID 24831815, 2014).
infection (1 paper, 2020). The state of being infected such as from the introduction of a foreign agent such as serum, vaccine, antigenic substance or organism. "Accordingly, the least ABCG1, ABCA1 and ACAT1 proteins in BCG-infected RAW264.7 cells were found at 12 h post infection, while the least ABCA5 and ABCA6 were at 24 h post infection." (PMID 32397995, 2020). "Of interest, the least ABCA1 and ACAT1 proteins in BCG-infected bovine AMs were observed at post infection 6 h, while the ABCG1 was at 12 h, and the least ABCA5 and ABCA6 were at 24 h post infection." (PMID 32397995, 2020).
ABCA5 also shares sentences with these, for which no sentence is quoted: melanoma (2 papers); acute myeloid leukemia (1); asthma (1); autism (1); bladder cancer (1); brain tumors (1); breast tumors (1); colon adenocarcinoma (1); Congenital Generalized Hypertrichosis Terminalis (1); cystic fibrosis (1); dilated cardiomyopathy (1); glioma (1); Hypercholesterolemia (1); ischemic stroke (1); kidney chromophobe (1); laryngeal squamous cell carcinoma (1); lung carcinoma (1); malignant mesothelioma (1); neurological disease (1); Niemann-Pick disease type C (1); polycystic ovary syndrome (1); retinal degeneration (1); tenosynovial giant cell tumor (1); thymoma (1); thyroid carcinoma (1); uterine corpus endometrial carcinoma (1).